COL2A1 (collagen type II alpha 1 chain)
Description:
Type II collagen is specific for cartilaginous tissues. It is essential for the normal embryonic development of the skeleton, for linear growth and for the ability of cartilage to resist compressive forces.
Synonyms: STL1; ACG2; ANFH; ANFH1; AOM; COL11A3; EDMMD; LCPD; OSCDP; PLSDT; SEDC; SEDSTN; SEMDSTWK; SMDALG; VPED
Tractability: Small molecule: a structure with a bound ligand is known; it has a binding pocket of medium quality. Antibody: its Gene Ontology location is reachable by antibodies, with high confidence; UniProt places it where antibodies can reach, with medium confidence; UniProt predicts a signal peptide or a membrane-spanning region. PROTAC: ubiquitination databases record sites on it; a small molecule that binds it is known. Other modalities: an approved drug acts on it.
Target class: Structural protein
Gene: Protein-coding gene on chromosome 12 (47,972,967 to 48,004,689, reverse strand). Ensembl gene ENSG00000139219.
Subcellular location: Secreted, extracellular space, extracellular matrix
Subcellular location (Human Protein Atlas): Nucleoplasm; Predicted to be secreted
Pathways (Reactome):
Extracellular matrix organization: Assembly of collagen fibrils and other multimeric structures; Collagen biosynthesis and modifying enzymes; Collagen chain trimerization; Collagen degradation; ECM proteoglycans; Fibronectin matrix formation; Integrin cell surface interactions; Non-integrin membrane-ECM interactions
Developmental Biology: Developmental Lineage of Pancreatic Ductal Cells; NCAM1 interactions
Signal Transduction: MET activates PTK2 signaling; Signaling by PDGF
Immune System: Immunoregulatory interactions between a Lymphoid and a non-Lymphoid cell
Gene Ontology:
Molecular function: extracellular matrix structural constituent; extracellular matrix structural constituent conferring tensile strength; MHC class II protein binding; platelet-derived growth factor binding; protein homodimerization activity; proteoglycan binding; identical protein binding
Biological process: chondrocyte differentiation; collagen fibril organization; embryonic skeletal joint morphogenesis; sensory perception of sound; skeletal system development; visual perception; cartilage development; skeletal system morphogenesis; animal organ development; central nervous system development; limb bud formation; notochord development; ossification; otic vesicle development; system development
Cellular component: collagen type II trimer; collagen type XI trimer; extracellular matrix; extracellular region; endoplasmic reticulum lumen; basement membrane; collagen trimer; cytoplasm; fibrillar collagen trimer
Genetic constraint (gnomAD): Loss-of-function variants: 26 observed, 196.9 expected, observed/expected ratio (o/e) 0.13, 90% interval 0.096 to 0.18. The upper end of that interval is the gene's LOEUF score, 0.18, which puts it in group 1 of 6, group 1 being the genes least tolerant of losing a copy. Missense variants: 1,381 observed, 2,048.7 expected, observed/expected ratio (o/e) 0.67, 90% interval 0.64 to 0.7. Synonymous variants: 708 observed, 724.28 expected, observed/expected ratio (o/e) 0.98, 90% interval 0.92 to 1.04.
Gene-disease validity (ClinGen):
ClinGen rates the evidence that COL2A1 causes each of these diseases.
achondrogenesis type II (autosomal dominant): Definitive.
COL2A1-related spondyloepiphyseal dysplasia (autosomal dominant): Definitive. Any spondyloepiphyseal dysplasia in which the cause of the disease is a variant in the COL2A1 gene.
dysplasia of the proximal femoral epiphyses (autosomal dominant): Definitive. A developmental disorder affecting the growth and development of the proximal end of the femur (thigh bone) near the hip joint characterized by avascular necrosis of the femoral head, cystic changes of the femoral head, and/or sclerosis of the femoral head.
Kniest dysplasia (autosomal dominant): Definitive. A rare type 2 collagen-related bone disorder characterized by moderately severe chondrodysplasia with disproportionate short stature of prenatal onset, prominent joints with restricted mobility, large epiphyses and dumbbell deformity of the long bones.
platyspondylic dysplasia, Torrance type (autosomal dominant): Definitive.
spondyloperipheral dysplasia (autosomal dominant): Definitive.
Stickler syndrome type 1 (autosomal dominant): Definitive.
spondyloepiphyseal dysplasia, Stanescu type (autosomal dominant): Moderate.
Homologues: Orthologues: chimpanzee COL2A1 (99% identical), macaque COL2A1 (99% identical), dog COL2A1 (98% identical), pig COL2A1 (98% identical), rabbit COL2A1 (97% identical), guinea pig COL2A1 (96% identical), rat Col2a1 (96% identical), mouse Col2a1 (95% identical), tropical clawed frog col2a1 (87% identical), zebrafish col2a1a (82% identical), zebrafish col2a1b (75% identical). Paralogues in human: COL1A1 (71% identical), COL5A2 (65% identical), COL3A1 (61% identical), COL1A2 (59% identical), COL5A1 (45% identical), COL11A1 (45% identical), COL11A2 (43% identical), COL5A3 (40% identical), COL4A5 (38% identical), COL4A1 (38% identical), COL4A3 (36% identical), COL4A4 (35% identical), and 25 more.
Diseases named in the same sentence as COL2A1 in open-access papers:
COL2A1 is named in the same sentence as 239 diseases in open-access papers, as found by Europe PMC text mining. Sharing a sentence is not in itself a finding about the gene and the disease. The quoted sentences say what the papers report.
Stickler syndrome (86 papers, 2007 to 2026). Stickler syndrome is an inherited vitreoretinopathy characterized by the association of ocular signs with more or less complete forms of Pierre-Robin sequence, bone disorders, and sensorineural deafness (10% of cases). "Stickler syndrome is a monogenic connective tissue disorder primarily caused by pathogenic variants in collagen-related genes, most commonly COL2A1." (PMID 41828453, 2026). "The most common form is Stickler Syndrome type 1 (STL1), which follows an AD inheritance pattern and is caused by heterozygous variants that result in loss of function of the COL2A1 gene, leading to haploinsufficiency." (PMID 40727136, 2025). "Stickler Syndrome, primarily caused by variants in COL2A1 and COL11A1, represents the most common form, accounting for approximately 80%–90% of cases." (PMID 40270540, 2025). "COL2A1-associated Stickler syndrome and the CSNB group had the most consistent refractive errors, with no patient being hyperopic." (PMID 41465105, 2025). "Biallelic pathogenic mutations in COL9A1 have also been associated with Stickler syndrome with ocular abnormalities, alongside more common causes of Stickler syndrome caused by mutations in COL2A1 and COL11A1." (PMID 41153400, 2025). "In summary, clinicians should consider offering prophylactic laser retinopexy for patients with Stickler syndrome, especially for patients with COL2A1 pathogenic variants and high myopia." (PMID 41153400, 2025). "Truncating variants in COL2A1 cause Stickler syndrome, a connective tissue disorder characterized by ocular, auditory, and skeletal abnormalities, via haploinsufficiency." (PMID 40666329, 2025). "The most common form of Stickler syndrome (COL2A1) is characterized by mild to high hearing loss due to deficiency in Col2A1, Col9A1, Col9A2, Col9A3 gene expression." (PMID 38376199, 2024). "Mutations in Col1a2 are associated with osteogenesis imperfecta, while mutations in Col2a1 and Col9a2 are linked to Stickler syndrome." (PMID 38413848, 2024). "Stickler syndrome (N = 2; causative variant in the COL2A1 gene) and Pitt-Hopkins syndrome (N = 3; one causative variant in the TCF4 gene, two cases associated with 18q deletion syndrome) were most common in this cohort." (PMID 39495751, 2024). "In 2019, we expended genetic testing which revealed the variant in the COL2A1 gene (NM_001844.5) c.375+1G>A[=], confirming the Stickler syndrome." (PMID 37384046, 2023). "The nonsense variant in COL2A1 (NM_001844.5:c.2659C>T; p.Arg887Ter) was previously reported in Clinvar, as implicated in Stickler syndrome." (PMID 36830605, 2023). "The most highly expressed top-scoring gene, COL2A1, has been linked to Stickler syndrome, which includes CF abnormalities like cleft palate and midfacial hypoplasia." (PMID 37532691, 2023). "Eight individuals clinically displayed Stickler Syndrome, seven of whom had genetic confirmation, and two different COL2A1 mutations (c.3641delC and c.3853G>T) were identified." (PMID 37107605, 2023). "By contrast, Stickler syndrome has the most collagens (six) linked to this syndrome (COL2A1, COL9A1, COL9A2, COL9A3, COL11A1, and COL11A2), followed by Ullrich congenital muscular dystrophy, with four collagens associated (COL6A1, COL6A2, COL6A3, and COL12A1)." (PMID 37189830, 2023). "In all reports where genetic confirmation of Stickler syndrome was conducted prior to performing surgical prophylaxis, the patients had Type 1 Stickler syndrome, caused by mutations in COL2A1." (PMID 35885933, 2022). "Pathogenic variants in COL2A1 causing Stickler syndrome usually result in haploinsufficiency of the protein, whereas pathogenic variants of type XI collagen more usually exert dominant negative effects." (PMID 35741851, 2022). "In fact, COL2A1 glycine mutations p.Gly144Val and p.Gly267Asp cause the prototypical COL2A1-disease Stickler syndrome." (PMID 35163424, 2022).
Stickler syndrome (continued). "The majority of pathogenic variants that cause the ocular-only variant of Stickler syndrome are missense and nonsense mutations that affect exon 2 of COL2A1." (PMID 35741851, 2022). "Most cases of Stickler syndrome are due to autosomal-dominant COL2A1 gene mutations leading to abnormal type II collagen." (PMID 36278547, 2022). "Pathogenic variants of the COL2A1 gene that typically cause type 1 Stickler syndrome are usually premature stop codons or frameshift mutations that lead to nonsense-mediated decay of the mRNA transcript, resulting in haploinsufficiency of type II collagen." (PMID 35741851, 2022). "The known causative genes of Stickler syndrome are COL2A1, COL11A1, COL11A2, COL9A1, COL9A2, and COL9A3." (PMID 34680973, 2021). "Retinal detachment in Stickler syndrome type 1, which is caused by COL2A1 pathogenic variants, can be prevented by prophylactic cryotherapy." (PMID 35052368, 2021). "Type 1 Stickler Syndrome, caused by mutations in COL2A1 (the gene encoding the α-1 chain for Type II collagen) accounts for more than 80% of Stickler Syndrome patients." (PMID 32901364, 2021). "LMX1A is known for AD or AR nonsyndromic hearing loss, while COL2A1 is related to Stickler syndrome type 1 with hearing loss (MIM 108300) as well as various skeletal phenotypes." (PMID 33924653, 2021). "Stickler syndrome caused by COL2A1, COL11A1, and COL11A2 genes has a dominant inheritance, whereas COL9A1, COL9A2, and COL9A3 genes show a recessive inheritance." (PMID 34680973, 2021). "In allele heterogeneity, the same DGP causes more D. For instance, the DGP encoded by the COL2A1 gene (a collagen subunit) causes 14 collagenopathies, including the Stickler syndrome." (PMID 33622316, 2021). "In this study, we report genetic analysis of 37 Korean patients with Stickler syndrome, which revealed 21 variants including 11 novel variants in COL2A1 and COL11A1." (PMID 34680973, 2021). "Loss-of-function variants in COL2A1 cause type 1 Stickler syndrome, with vitreous anomaly and significant risk of retinal detachment." (PMID 30568244, 2019). "The patient also fulfills the proposed criteria for Stickler syndrome with bifid uvula, hearing loss, and a known mutation in COL2A1." (PMID 30170566, 2018). "In humans, mutations in COL2A1 cause Stickler syndrome, a genetic disorder affecting the connective tissue; however, no renal defects are known to be associated with this syndrome." (PMID 30166318, 2018). "P6 carried the known pathogenic variant p.R904C of COL2A1 and was diagnosed with Stickler syndrome by gene screening." (PMID 30541462, 2018). "A p.R904C variant of the COL2A1 gene was found in a patient, who was accordingly diagnosed with Stickler syndrome." (PMID 30541462, 2018). "In this case report, we identify a novel missense mutation in the COL2A1 gene in a patient with Stickler syndrome type 1, and we describe age-related changes in the clinical phenotype with regard to orofacial characteristics and height." (PMID 28841907, 2017). "Stickler syndrome type 1 (STL1) [MIM:108300] is the most common type, caused by mutations in the COL2A1 [MIM:120140] gene on chromosome 12q13.11." (PMID 28841907, 2017). "In summary, mutations in the COL2A1 gene were found in 21 of 23 Japanese families (91.3%) with Stickler syndrome." (PMID 27408751, 2016). "We report an Indian boy having 2710C>T mutation in COL2A1 gene demonstrating short stature, ptosis, and uveitis with Stickler syndrome." (PMID 28018693, 2016). "The purpose of this study was to determine the phenotype–genotype correlation in Japanese patients with Stickler syndrome caused by mutations in the COL2A1 gene." (PMID 27408751, 2016). "One mouse knockout allele of Col2a1 displays cardiac valve abnormalities, and mutations in both genes are associated with Stickler syndrome where 46% of patients are affected with congenital dysfunction of the mitral valve." (PMID 27058611, 2016).
Stickler syndrome (continued). "The proband of Family #22 has the typical signs of type 1 Stickler syndrome and probably has an intronic or severe truncating loss-of-function mutation in the COL2A1 gene." (PMID 27408751, 2016). "Stickler syndrome is commonly caused by mutations in different collagen genes, namely COL2A1, COL11A1 and COL11A2 (autosomal dominant inheritance) and COL9A1 and COL9A2 (autosomal recessive inheritance)." (PMID 26307084, 2015). "In humans, Stickler syndrome caused by mutations of COL2A1, COL11A1, COL11A2, COL9A1 and COL9A2, is one of the most common connective tissue disorders characterized by ocular, skeletal, orofacial and auditory defects." (PMID 26307084, 2015). "COL2A1 was found to be involved in sensorineural deafness that is associated with hereditary syndromes in humans, like Stickler syndrome, spondyloepiphyseal dysplasia congenita (SEDC), and chondrodysplasia." (PMID 22567353, 2011). "Variants of Stickler syndrome have been designated STL1 (vitreous type with mutations in COL2A1 gene), STL2 (early onset hearing loss and mutations in the COL 11A1 gene) and STL3 (non-ocular type caused by mutations in the COL11A2 gene)." (PMID 18950500, 2008). "Numerous genetic mutations of Stickler syndrome cases are STL1 variety and are caused by mutations in the COL2A1 gene." (PMID 18950500, 2008). "The candidates in this study were used in previous investigations of single gene disorders predisposed to myopia (COL2A1 and Stickler Syndrome, COL18A1 and Knobloch Syndrome)." (PMID 17653045, 2007). "Interestingly, the Arg453Ter mutation in exon 30 of COL2A1, which was previously reported in patients with classic Stickler syndrome, has also been associated with OSTL1." (PMID 41050055, 2025). "Mutations in the COL2A1 gene result in Stickler syndrome which often characterized by high myopia." (PMID 38790056, 2024). "The ocular-only subgroup of Stickler syndrome has to date only been reported to be caused by variants located in the COL2A1 gene, largely as a consequence of missplicing of exon 2, which is excluded in the protein in mature cartilage but included within ocular tissue." (PMID 38153936, 2023). "In addition, we also discovered the variant in the COL2A1 gene (NM_001844.5) c.375+1G>A[=], confirming the Stickler syndrome." (PMID 37384046, 2023). "The COL2A1 gene implicated in type 1 Stickler syndrome expresses the α1 chain of type II collagen." (PMID 35741851, 2022). "The first mutation in a Stickler syndrome family was found in the COL2A1 gene in 1991." (PMID 36140739, 2022). "The precision care included cryotherapy to prevent retinal detachment in COL2A1 Stickler syndrome, osteoporosis management in patients with LRP5-associated familial exudative vitreoretinopathy, and avoidance of unnecessary phlebotomy in hyperferritinemia-cataract syndrome." (PMID 35052368, 2021). "Collagen type II alpha 1 (COL2A1) is a fibrillar collagen found in the vitreous humour and mutations in this gene are associated with Stickler syndrome in which patients suffer from ocular pathologies such as vitreous degeneration, high myopia, retinal detachment and cataracts." (PMID 33934486, 2021). "Various types of mutations in COL2A1 have been reported, and truncation mutations (nonsense, frameshift, or splicing) that result in a premature stop codon are present in most patients with Stickler syndrome." (PMID 32756486, 2020). "Interestingly, all three collagen genes (Col2a1, Col9a1, Col11a1) related to extracellular matrix degradation and enriched in expression in the peripheral retina are known to cause the Stickler Syndrome." (PMID 31108889, 2019). "It is estimated that 80%–90% of all Stickler syndrome cases are associated with pathological variants in COL2A1 (Type I), 10%–20% of cases are COL11A1-related (Type II), and Types III-VI are rare and of an unknown prevalence." (PMID 28335520, 2017). "Twenty-one mutations (91.3%) in the COL2A1 gene were found in 23 families with Stickler syndromes." (PMID 27408751, 2016).